GNAQ (G protein subunit alpha q)
Diseases named in the same sentence as GNAQ in open-access papers (continued):
Sharing a sentence is not in itself a finding about the gene and the disease.
uveal melanoma (continued). "Somatic mutations in GNAQ gene were described as being the main oncogenic activation in uveal melanomas, whereas mutations in BRAF gene have been described as a key genetic alteration that contributes to skin melanoma development." (PMID 23904987, 2013). "We also found an oncogenic mutation in the G protein alpha subunit, GNAQ, which couples to Endothelin receptor B, in a uveal melanoma from a patient with neurofibromatosis type 1." (PMID 23555837, 2013). "The majority of uveal melanomas bear a mutually exclusive activating mutation in either GNAQ or GNA11, resulting in overlapping functions in melanoma cells with the constitutive upregulation of the MAPK pathway." (PMID 22515704, 2012). "Recently, a mutation at Q209 in the GNAQ paralogue gene GNA11 that also activates MAPK signaling was discovered in over 30% of uveal melanomas." (PMID 22808163, 2012). "While GNAQ is primarily viewed as relevant to uveal melanoma, anecdotal reports have found mutations in this gene in non-uveal melanoma patients as well." (PMID 21479172, 2011). "INPP5A was recently identified as a drug target in uveal melanoma (UVM) with activating mutations in the guanosine nucleotide-binding protein Q gene (GNAQ) or its paralog guanosine nucleotide-binding protein alpha-11 gene (GNA11), which occur in approximately 90% of these cancers." (PMID 39995872, 2025). "A study indicated that metastasized uveal melanomas exhibited mutations in GNAQ and BAP1." (PMID 40598734, 2025). "Furthermore, sequencing of exon 4 of both GNA11 and GNAQ genes, affecting codon R183 (arginine 183), showed a lower prevalence of mutations: 4.9% of primary uveal melanomas and 2.1% of blue nevi." (PMID 39518110, 2024). "Uveal melanoma (UM) is an aggressive cancer emerging from mutations in the GNAQ and GNA11 genes." (PMID 39518110, 2024). "However, greater than 80% of uveal melanomas have activating mutations in GNAQ or GNA11, genes that encode for G protein alpha subunits." (PMID 38683104, 2024). "Overall, 83% of all investigated uveal melanomas had oncogenic mutations in either GNA11 or GNAQ." (PMID 39518110, 2024). "The mutated GNAQ gene is a proto-oncogene of uveal melanoma, and the activation of the pathway containing the mutated GNAQ may be the main cause of uveal melanoma." (PMID 37546388, 2023). "According to preliminary research, uveal melanoma with mutations in GNAQ and GNA11 is responsive to MEK inhibitors and could be used as a model for medical treatment for CH." (PMID 37106420, 2023). "Following the activation of PKC, the RAS-dependent extracellular signal-regulated kinase (ERK1/2) pathway activates rapidly accelerated fibrosarcoma (RAF)/MAPK, a pathogenic pathway that allows GNAQ-mutated uveal melanoma to progress and eventually become metastatic." (PMID 37576814, 2023). "A total of 99 of these 118 patients (84%) had detectable ctDNA at baseline and on treatment, of whom 94 had mutations detected in one or more uveal melanoma genes (GNAQ, GNA11, SF3B1, PLCB4, CYSLTR2) at a variant allelic frequency of >0.3 at baseline and were included in the analyses." (PMID 36229663, 2022). "In particular, hot spot mutations in GNAQ and GNA11, referred to as GNAQ oncogenes, encoding GTPase-deficient and constitutively active Gαq proteins, have been identified in ∼93% of uveal melanoma (UM) and 4% of skin cutaneous melanoma, where they act as driver oncogenes." (PMID 36596361, 2022). "Our analysis also shows frequent mutations of GNAQ in the TCGA UVM (uveal melanoma) cohort." (PMID 35975235, 2022). "We identified BRAF mutations in 21/74 (28%) patients, NRAS mutations in 4/74 (5.4%) patients, NF1 mutations in 1/74 (1.4%) patients and GNAQ mutations in 1/74 (uveal melanoma) (1.4%) patients, as well as BRAF/NRAS (1/74; 1.4%) and GNAQ/NF1 (1/74; 1.4%) double mutations." (PMID 32785074, 2020). "However, only a few studies have reported somatic mutations in GNAQ or GNA11 in uveal melanoma in Chinese." (PMID 35693877, 2019).
uveal melanoma (continued). "Several tumors, including uveal melanoma, show somatic mutations of GNAQ/GNA11." (PMID 31336681, 2019). "In light of the finding of these mutational hotspots in GNAQ and GNA11 in Caucasians, we hypothesized that somatic mutations in GNAQ or GNA11 may also be frequently observed in uveal melanoma in the Chinese population." (PMID 35693877, 2019). "Since primary uveal melanoma tumours and liver metastases, characterised by mutations in GNAQ or GNA11, have constitutive activation MAPK signalling via alternative, similar therapies targeting downstream effectors of the MEK pathway, Akt and protein kinase C (PKC) were recently investigated." (PMID 31109147, 2019). "Interestingly, in a subsequent study in uveal melanoma, mutations in GNAQ and GNA11 were found to promote YAP/TAZ activity." (PMID 29642615, 2018). "Furthermore, greater than 80% of uveal melanomas possess oncogenic mutations in G-protein-α subunits associated genes GNAQ or GNA11 as found in our case." (PMID 29433557, 2018). "Somatic mutations in GNAQ are frequent in uveal melanoma and single blue nevi." (PMID 26778290, 2016). "The use of MEK1/2 inhibitors has been suggested as a therapy for GNAQ-mutated uveal melanomas." (PMID 27057633, 2016). "Importantly, 80–96 % of uveal melanomas harbour mutations in either the guanidine nucleotide binding protein (G protein), Q polypeptide 1 (GNAQ) or the G protein alpha 11 (GNA11) gene, in a mutually exclusive pattern." (PMID 26059332, 2015). "GNA11 has a stronger association with metastatic uveal melanoma than GNAQ." (PMID 24743024, 2014). "The most significant single chromosomal marker of poor outcome in uveal melanoma is loss of one copy of chromosome 3, while activating mutations in the alpha subunit of heterotrimeric G proteins, GNAQ or GNA11, are considered an early event in the development of the disease." (PMID 25166211, 2014). "Interestingly, GNAQ/11 mutations were associated with uveal melanomas involving optic disc in our study." (PMID 25280020, 2014). "We hypothesized that an increased melanoma risk in familial melanoma families with uveal melanoma and/or blue nevi is due to GNAQ and GNA11 germ-line mutations in exon 5 which result in constitutive activation of the MAPK pathway." (PMID 23825798, 2013). "Mutations in GNAQ were found in 46% of uveal melanomas and 27% of uveal melanoma cell lines." (PMID 25562798, 2012). "In the article, we attempt to comprise knowledge available from clinical trials and meta-analyses and assess whether there is any correlation between the occurrence of benign skin blue nevi or hemangiomas with uveal melanoma and other medical conditions caused by GNAQ and GNA11 mutations." (PMID 39518110, 2024). "The G protein α-subunit GNAQ is mutated in 46% of uveal melanomas and 84% of blue nevi samples and is less frequently (2.4%) altered in cutaneous melanoma, suggesting that DNMT3A loss of function may be more impactful for melanoma development in certain contexts." (PMID 37160317, 2023). "Our study did not allow addressing whether the association between GNAQ/11 mutations and uveal melanomas involving optic disc would be a parallel to the previous observation of two choroidal melanocytomas harboring mutations in GNAQ with one of them transforming into uveal melanoma." (PMID 25280020, 2014). "The first mutation set encompasses the eight UM driver genes according to the TCGA study, divided into “uveal melanoma initiating mutations” (CYSLTR2, GNA11, GNAQ and PLCB4) and “second hit mutations with prognostic impact” (BAP1, EIF1AX, SF3B1 and SRSF2)." (PMID 39858540, 2025). "Background/Objectives: Uveal melanoma (UVM), the leading primary intraocular cancer in adults, is driven by GNAQ/GNA11 mutations, encoding the active forms of Gαq proteins." (PMID 41514587, 2025). "The MAPK cascade, initiated by common activating mutations in GNAQ and GNA11, is the main oncogenic pathway driving uveal melanoma." (PMID 41154654, 2025).
uveal melanoma (continued). "Genetics and immunology will be cutting-edge research areas in uveal melanoma, with attention to genes such as GNAQ, GNA11, and BAP1, highlighted as important focus points." (PMID 39898362, 2025). "Mutations in GNAQ and GNA11 are predominantly found in uveal melanoma, a type of melanoma originating in the eye." (PMID 39200315, 2024). "Due to its essential cellular functions, the GNAQ gene is considered a proto-oncogene, especially referring to melanocytes and uveal melanomas." (PMID 39518110, 2024). "In a clinical study, patients treated with darovasertib demonstrated a 50% reduction in tumor size, highlighting the potential of targeting GNAQ and GNA11 mutations to develop effective treatments for uveal melanoma." (PMID 39200315, 2024). "This meta-analysis aimed to evaluate the prognostic significance of driver mutations, including GNAQ, GNA11, BAP1, and SF3B1, in the advancement of uveal melanoma." (PMID 39061150, 2024). "A key oncogenic event in uveal melanoma is the activation of YAP, resulting from mutations in GNAQ or GNA11, which encode α subunits of the Gq family of G proteins." (PMID 38182898, 2024). "Mutations in G-protein subunits, specifically GNAQ and GNA11, are prevalent in uveal melanoma, occurring in approximately 85% of cases in a mutually exclusive pattern." (PMID 39061150, 2024). "In uveal melanoma (UM), characterized by activating mutations in GNAQ/GNA11, encoding the Gαq protein, FAK has been identified as a central mediator of Gαq-driven signaling." (PMID 38410129, 2024). "Our analysis suggests that the majority of TWT cutaneous melanomas harbor a Ras/MAPK pathway mutation, with some confirmed cutaneous melanomas demonstrating mutations more commonly identified in uveal melanoma, including EIF1AX and GNAQ." (PMID 38611025, 2024). "GNAQ/GNA11 mutations, commonly identified in uveal melanomas, represent a distinct genetic subgroup within melanoma." (PMID 38474231, 2024). "Uveal melanoma-related genes (BAP1, SF3B1, GNAQ/11) can also be mutated in CMs, albeit infrequently." (PMID 37761808, 2023). "Recent phosphoproteomic and genome-wide synthetic lethality strategies and chemogenetic drug screening have revealed novel targetable signaling vulnerabilities in GNAQ-driven uveal melanoma." (PMID 37958718, 2023). "The distribution of GNAQ and GNA11 mutation signatures also provides further supporting molecular evidence for a light or UV exposure dependent mechanism in uveal melanoma." (PMID 35338357, 2023). "Mutations in the GNAQ/GNA11 gene activate the MAP kinase signaling pathway, a key factor in the development of uveal melanoma." (PMID 37628631, 2023). "Somatic p.Gln209 mutations in GNAQ cause most uveal melanomas, and, as mosaic mutations of GNA11 or GNAQ, cause Sturge–Weber and other cutaneous syndromes." (PMID 37612380, 2023). "Major genetic drivers identified in uveal melanoma include early events activating GNAQ (at 9q21) or GNA11 (at 19p13) and later events involving EIF1AX (at Xp22) or SF3B1 (at 2q33) or BAP1 (at 3p21)." (PMID 37761808, 2023). "Somatic mutations of GNA11/GNAQ, which excessively activate the MEK/ERK signaling pathway, are the most common cause of uveal melanoma with hotspot mutations mainly affecting Q209 and R183 residues." (PMID 37658401, 2023). "Both GNAQ and GNA11 pGlu209Leu missense variants identified in patients with CHs are also common mutations in uveal melanoma and have been shown to constitutively activate MAPK and/or YAP (Yes-Associated Protein) signaling." (PMID 36293054, 2022). "Both GNAQ and GNA11 genes codify for α-subunits of G-coupled proteins and have been recognized as uveal melanoma driver mutations." (PMID 35409195, 2022). "The role of GNAQ as an oncogene has been observed in uveal melanoma, blue nevi, and malignancies affecting the meninges." (PMID 35864526, 2022). "Activation of NOTCH signaling was reported to play a key role downstream of oncogenic GNAQ in uveal melanoma cells." (PMID 35673577, 2022).
uveal melanoma (continued). "The GNAQ and GNA11 genes are mutated in almost 80–90% of uveal melanomas in a mutually exclusive pattern." (PMID 35804836, 2022). "A recent study suggested that combining the HDI entinostat with dual human epidermal growth factor 2 and the epidermal growth factor receptor neratininb leads to internalization and degradation of mutant GNA11 and GNAQ in uveal melanoma models." (PMID 34533562, 2021). "Activating Gαq signalling mutations at mutually-exclusive hotspots in GNAQ and GNA11 (p.Q209 and p.R183) are found in a large majority of uveal melanomas." (PMID 33588787, 2021). "Taken together, these findings indicate that mutations in GNAQ, GNA11 and CYSLTR2 – all recurrently found in uveal melanomas – can also present as an independent somatic event in benign uveal nevi." (PMID 33588787, 2021). "As mentioned, activating GNAQ and GNA11 mutations were first identified in cutaneous blue nevi and uveal melanoma." (PMID 34040639, 2021). "Uveal melanoma (UM) has well-characterised somatic copy number alterations (SCNA) in chromosomes 1, 3, 6 and 8, in addition to mutations in GNAQ, GNA11, CYSLTR2, PLCB4, BAP1, SF3B1 and EIF1AX, most being linked to metastatic-risk." (PMID 32340176, 2020). "Minor percentages of melanomas have activating mutations in the KIT gene, most common in mucosal melanomas derived from the genital regions or mutations in G Protein Subunit Alpha 11 (GNA11) or G Protein Subunit Alpha q (GNAQ) genes in uveal melanomas." (PMID 30884760, 2019). "In conclusion, this study found that somatic mutations in GNAQ and GNA11 occur frequently in uveal melanoma in Chinese people." (PMID 35693877, 2019). "Genes that were known to be mutated in cutaneous and uveal melanoma subtypes, including BRAF, NRAS, NF1, GNAQ and GNA11, were rarely mutated in our cohort of patients." (PMID 30847022, 2019). "The high frequency of Q209 mutations and the large number of novel missense mutations found in this study suggest that somatic mutations in GNAQ and GNA11 are also frequent in uveal melanoma in Chinese people." (PMID 35693877, 2019). "Analysis of the GNA11 and GNAQ genes in two metastatic uveal melanomas revealed GNA11 p.Q209L and GNAQ p.Q209P, respectively." (PMID 31277584, 2019). "Mutations in GNAQ (50%) and GNA11 (44%) are early events that promote cell proliferation, suggesting that activated G-protein signaling plays a crucial role in early uveal melanoma development." (PMID 31598164, 2019). "We extracted somatic DNA from paraffin-embedded biopsies of 63 Chinese uveal melanoma samples and sequenced the entire coding regions of exons 4 and 5 in GNAQ and GNA11." (PMID 35693877, 2019). "Mutations in NRAS only occur in 10–20% of mucosal melanomas, while mutations in GNAQ and GNA11 that are commonly detected in uveal melanoma, occur in approximately 9.5% of mucosal melanomas." (PMID 30847022, 2019). "A panel of human uveal melanoma cell lines, including mutants in GNAQ, GNA11, and wild type were treated with a dose range of Tris DBA palladium, and cell number was evaluated at 24 hours." (PMID 31320995, 2019). "The high mutation frequency of Q209 and the novel missense mutations detected in this study suggest that GNAQ and GNA11 are common targets for somatic mutations in Chinese uveal melanoma." (PMID 35693877, 2019). "Recently, the use of inhibitors of MAPK pathway and its downstream effectors has shown promise in treating GNAQ mutant uveal melanoma." (PMID 35693877, 2019). "The activation of the mitogen-activated protein kinase (MAPK) pathway has been suggested as the major downstream target when GNAQ and GNA11 (GNAQ/11) are mutated in uveal melanoma (UM)." (PMID 31173078, 2019). "Second, it appears to be genetically distinct from cutaneous melanoma, with driver mutations in GNAQ and GNA11 being most common in uveal melanoma, while Braf and Nras are the most common driver mutations in cutaneous melanoma." (PMID 31320995, 2019).
uveal melanoma (continued). "Driver mutations in GNAQ and GNA11 were identified in two uveal melanomas, and a driver mutation in KIT was found in mucosal melanoma." (PMID 29991680, 2018). "Another study carried out by the same investigators showed frequent mutations in uveal melanoma of the gene GNA11, encoding for a GNAQ paralogue." (PMID 29156643, 2017). "Activating mutations in GNAQ and GNA11, which are commonly detected in uveal melanoma, have recently been reported to occur in 9.5% of mucosal melanomas, a finding not reported in previous studies." (PMID 28380455, 2017). "Two alterations were identified in GNAQ and GNA11, mutations that are usually associated with uveal melanomas and blue nevi." (PMID 28380455, 2017). "In this context, it is of interest to note that some mucosal melanomas exhibited mutated genes such as GNAQ and SF3B1, previously observed in uveal melanoma." (PMID 29156643, 2017). "Point mutations in GNAQ and GNA11 have been identified in 80–90% of uveal melanomas and lead to activation of the MAPK/MEK/ERK pathway." (PMID 29326884, 2017). "Uveal melanomas, in contrast to conjunctival melanomas, lack BRAF or NRAS mutations but frequently have mutations in GNAQ, GNA11, BAP1, SF3B1 or EIF1AX." (PMID 28938534, 2017). "Overall, these results collectively demonstrate two future possibilities to amerliorate GNAQ/11-induced uveal melanoma; reduction of Gαq/11-Q209L driver oncoprotein levels through Ric-8A inhibition or phorbol ester treatment." (PMID 27348266, 2016). "The heterotrimeric G protein α subunit oncogenes GNAQ or GNA11 carry Q209X or R183X activating mutations and are present with ~90% frequency in human uveal melanomas." (PMID 27348266, 2016). "With respect to the signaling pathways altered in these tumors, mutations in GNAQ and GNA11 appear to activate the RAS pathway in MABN, uveal melanoma and other melanocytic lesions." (PMID 27057633, 2016). "GNAQ and GNA11 are oncogenes when mutated in certain types of melanocytic lesions, being extremely frequent in uveal melanoma, which forms from melanocytes located in the eye." (PMID 27148356, 2016). "Uveal melanoma most frequently carry mutations in the GNAQ, GNA11, and BAP1 genes, where GNAQ/GNA11 mutations are mutually exclusive." (PMID 25106493, 2014). "The detailed analysis of YAP activation by GNAQ in uveal melanoma helped identify a novel signaling mechanism controlling YAP function." (PMID 25526026, 2014). "These mutations remained undetected in uveal melanomas until recently GNAQ and GNA11 mutations in uveal melanoma were identified." (PMID 25280020, 2014). "In conclusion, mutations of GNAQ and GNA11 can be found in Chinese patients as in Caucasian patients with uveal melanoma, with the reported frequency being higher in Caucasian patients." (PMID 25280020, 2014). "Gene mutations in cutaneous melanoma (BRAF, N-Ras, etc.)were entirely different from those in uveal melanoma (GNAQ, GNA11, etc.)." (PMID 25184134, 2014). "Mutations in the genes GNAQ and GNA11 are critical for development and progression of uveal melanoma and are associated with activation of the mitogen-activated protein kinase (MAPK) pathway." (PMID 25030020, 2014). "GNAQ or GNA11 mutations lead to an upregulating activation of the MAPKinase pathway and appear to be major contributors to the development of uveal melanomas." (PMID 25280020, 2014). "Mutations in GNAQ and GNA11 are mutually exclusive and are present in the vast majority of uveal melanomas." (PMID 24743024, 2014). "Mutations of GNAQ and GNA11 can be found in Chinese patients as in Caucasian patients with uveal melanoma, with a higher frequency reported for Caucasian patients." (PMID 25280020, 2014). "GNAQ and GNA11 mutations, which are potential drivers of MAPK activation, have been reported in blue nevi and in up to 85% of cases of uveal melanoma." (PMID 25030020, 2014). "In this study we investigate the effect of MEKi and/or METi treatment on GNAQ mutant and wild-type uveal melanoma cell lines." (PMID 24551032, 2014).